MIR4735 (microRNA 4735)
Synonyms: hsa-mir-4735
Gene: MicroRNA gene on chromosome 1 (196,582,413 to 196,582,481, reverse strand). Ensembl gene ENSG00000265986.
Homologues: Orthologues: chimpanzee MIR4735 (100% identical).